CCL3 (C-C motif chemokine ligand 3)
Diseases named in the same sentence as CCL3 in open-access papers (continued):
Sharing a sentence is not in itself a finding about the gene and the disease.
hepatocellular carcinoma (12 papers, 2014 to 2025). A malignant tumor that arises from hepatocytes. "MMP-2 is involved in CCL3-dependent cell invasion in oral squamous cell carcinoma and chondrosarcoma, whereas MMP-9 is involved in CCL3-dependent cell invasion in hepatocellular carcinoma and oral squamous cell carcinoma." (PMID 32457351, 2020). "Hepatoma cell lines were found to produce increased levels of CCL3, which in turn stimulated these cells to produce pseudopodia and to migrate in vitro." (PMID 28881626, 2017). "Consistently, previous data showed that CCL3 induced pseudopodia formation in hepatoma cells." (PMID 28881626, 2017). "Besides this, CCL3 has been identified as recruiting leukocytes to hepatocellular carcinoma." (PMID 36012108, 2022). "CCL3 and CCL3L1 were found to be down-regulated in the samples of hepatic carcinoma with metastasis." (PMID 28427195, 2017). "In conclusions, CCL3, CCL3L1, JUN, IL8, and IL1B have the potential to be considered as candidates for future molecular diagnosis of the hepatic carcinoma with metastasis." (PMID 28427195, 2017). "CCL3, CCL3L1, JUN, IL8, and IL1B were identified in inflammation mediated by chemokine and cytokine signaling pathway (P00031) in the hepatic carcinoma samples with metastasis, and subsequently confirmed by quantitative real-time polymerase chain reaction." (PMID 28427195, 2017). "In the cultured cervical squamous carcinoma cells, hepatocellular carcinoma and lung adenocarcinoma, CCL3/MIP-1α expression is not elevated." (PMID 32781743, 2020). "Finally, in order to further validate these 5 DEGs, RT-qPCR were performed and the result was the same with that of RNA-seq, demonstrating that CCL3, CCL3L1, JUN, IL8, and IL1B were reliable and available to be used as the candidates for hepatic carcinoma with metastasis." (PMID 28427195, 2017). "On the other hand, a study demonstrated that the absence of CCL3/CCR1, but not CCL3/CCR5, resulted in a decreased incidence of hepatocellular carcinoma." (PMID 28881626, 2017).
Insulin resistance (12 papers, 2011 to 2023). Increased resistance towards insulin, that is, diminished effectiveness of insulin in reducing blood glucose levels. "As a top ranking gene, CCL3 encodes macrophage inflammatory protein 1α, a CC chemokine involved in the interactions between immune cells and regulated by insulin resistance in AT." (PMID 23028366, 2012). "Several studies have shown that elevated levels of CCL2, CCL3 and CCL11 are associated with insulin resistance contributing to the development of T2DM33." (PMID 38092892, 2023). "The genetic deletion of CCL3 attenuated the CL diet-induced steatohepatitis and hepatic insulin resistance, at least partly, by decreasing macrophage recruitment and restoring alternative macrophage activation in the liver." (PMID 35744024, 2022). "Similar to the findings in mice we could also demonstrate that TNFα and CCL3 levels correlated with fasting glucose HOMA-IR and NAFLD severity suggesting that similar pathogenic mechanisms may underlie the development of insulin resistance and NASH in humans." (PMID 27992443, 2016). "The chemokine CCL3 is up-regulated with insulin resistance in AT." (PMID 25590576, 2015). "Thus, inflamed adipose tissue could promote low-grade systemic inflammation by releasing proinflammatory cytokines and chemokines (IL-1ß, TNF-α, IL-6, leptin, CCL2, CCL3, and CXCL8) and causing insulin resistance and endothelial dysfunction." (PMID 28512338, 2017).
osteosarcoma (12 papers, 2016 to 2025). A usually aggressive malignant bone-forming mesenchymal neoplasm, predominantly affecting adolescents and young adults. "VEGF-A is involved in CCL3-dependent angiogenesis in osteosarcoma and is also upregulated downstream of the CCL3–CCR5 axis in oral squamous cell carcinoma." (PMID 32457351, 2020). "We found that the conditioned medium (CM) from CCL3-treated osteosarcoma cells promoted EPCs migration and tube formation (VEGF-A was used as positive control)." (PMID 26713602, 2016). "Here, using immunohistochemistry (IHC) analysis, we determined that CCL3 and VEGF-A expressions in osteosarcoma specimens from patients are associated with tumor grade, and are significantly higher compared to normal bone specimens." (PMID 26713602, 2016). "We treated osteosarcoma cells with various concentrations of CCL3 to determine the relationship between CCL3 and VEGF-A." (PMID 26713602, 2016). "The immunohistochemistry (IHC) result indicated that CCL3 expression is higher in osteosarcoma patients compared to normal individuals, and the expression profile of CCL3 is associated with the osteosarcoma clinical stage." (PMID 26713602, 2016). "In this study, we found the effect of CCL3 on VEGF-A production in human osteosarcoma, which is responsible for subsequent increased tumor angiogenesis." (PMID 26713602, 2016). "In human osteosarcoma cells, CCL3 promotes angiogenesis by dysregulation of VEGFa." (PMID 35154316, 2022). "Furthermore, EPC migration and tube formation, which were induced by CCL3-treated osteosarcoma cells CM, were also abolished." (PMID 26713602, 2016). "We found that CCL3 plays an important role in promoting VEGF-A expression and angiogenesis in human osteosarcoma cells, suggesting that CCL3 may be a novel target for metastasis and angiogenesis of osteosarcoma." (PMID 26713602, 2016). "Furthermore, the mRNA expression of CCL3 has positive correlation with VEGF-A in osteosarcoma patients." (PMID 26713602, 2016). "Furthermore, CCL3 promotes VEGF-A expression in human osteosarcoma cells that subsequently induces human endothelial progenitor cell (EPC) migration and tube formation." (PMID 26713602, 2016). "In conclusion, CCL3 is expressed at high levels in osteosarcoma and promotes VEGF-A expression." (PMID 26713602, 2016). "Hence, CCL3 promotes angiogenesis through VEGF-A-dependent expression in human osteosarcoma cells." (PMID 26713602, 2016). "In osteosarcoma, CD16+ monocytes/macrophages secrete chemokines CCL2, CCL3, and CCL8 to enhance tumor infiltration by immune cells." (PMID 41155410, 2025). "C-C Motif Chemokine Ligand 3 represses the expression of miR-374b, which subsequently accelerates VEGF-A level and angiogenesis in osteosarcoma cells." (PMID 32290826, 2020). "Together, we found that CCL3 induced VEGF-A expression and angiogenesis by activating JNK, ERK, and p38 pathways in human osteosarcoma cells." (PMID 26713602, 2016). "However, the role of CCL3 in human osteosarcoma cell is mostly unknown." (PMID 26713602, 2016). "To further confirm CCL3-mediated VEGF-A expression and angiogenesis in human osteosarcoma, we constructed MG-63 and U-2 OS cells stably expressing CCL3-shRNA." (PMID 26713602, 2016). "Taken together, these data indicating that CCL3 plays an important role in promoting VEGF-A expression and angiogenesis in human osteosarcoma cells." (PMID 26713602, 2016). "Here we demonstrate the correlation of CCL3 and VEGF-A expressions, quantified by immunohistochemistry, with the tumor stage of human osteosarcoma tissues." (PMID 26713602, 2016). "Here we show that CCL3 enhances tumor angiogenesis and VEGF-A expression by dysregulation of miR-374b via the JNK, ERK, and p38 pathways in human osteosarcoma." (PMID 26713602, 2016). "Thus, CCL3 may be a new molecular therapeutic target in osteosarcoma angiogenesis and metastasis." (PMID 26713602, 2016).
osteosarcoma (continued). "This study shows that CCL3 promotes VEGF-A expression and angiogenesis in human osteosarcoma cells by down-regulating miR-374b expression via JNK, ERK, and p38 signaling pathways." (PMID 26713602, 2016). "CCL3 increases angiogenesis and up-regulation of VEGF-A expression by down-regulating miR-374b through JNK, p38, and ERK pathways in human osteosarcoma cells." (PMID 26713602, 2016). "More interesting, we found many immune-related genes (including CCL3, CCL4, CCL4L2, and CXCL5) enriched in the thrombus samples of osteosarcoma, which indicates that multiple genes involved in immunological pathways may be activated concordantly." (PMID 37244923, 2023). "However, we found that miR-145, miR-29b and miR-410 only have less regulated by CCL3, and we revealed another miRNA (miR-374b) that could target VEGF-A, and inhibit angiogenesis in human osteosarcoma cells." (PMID 26713602, 2016). "Furthermore, the two CD8 + cytotoxic clusters demonstrated upregulation of NKG7, GZMB, GZMH, GZMK, CCL3, CCL4, and CCL5, suggesting that chemotherapy amplified the cytotoxic function of CD8 + T cells, potentially enhancing their antitumor activity within the osteosarcoma tumor microenvironment." (PMID 39033089, 2024). "In addition, the expression of miR-374b has negative correlation with CCL3 and VEGF-A in osteosarcoma patients, suggesting miR-374b plays a negative regulator in CCL3-induced VEGF-A expression and angiogenesis." (PMID 26713602, 2016). "However, the role of CCL3 in VEGF-A production and angiogenesis in human osteosarcoma cells has not yet been clarified." (PMID 26713602, 2016).
ZIKV infection (12 papers, 2017 to 2023). "Moreover, ZIKV infection induced an increase in the chemokines CCL3, CXCL9, and CXCL8, while CCL4 and CXCL11 were significantly decreased." (PMID 33430059, 2021). "ZIKV infection increases the levels of a series of cytokines (IL-1α, IL-6, IL-9, IL-10, IL-12p70, and IFN-γ) and chemokines (CCL2, CCL3, CCL4, CCL5, CCL11, and CXCL1) in mouse brain." (PMID 34399779, 2021). "Increased serum concentrations of both CXCL (CXCL8 and CXCL10) and CCL chemokines (CCL2, CCL3, CCL4, CCL5, and CCL11) were found in acute ZIKV infection." (PMID 29768624, 2018). "Acutely infected cells produced high levels of pro-inflammatory chemokines, including CCL2, CCL3, CCL4, CCL5 and CXCL8, which could contribute to CNS inflammation during ZIKV infection in vivo by promoting the recruitment of various leukocytes into the CNS." (PMID 32375993, 2020). "In our study, levels of several immune markers, such as IFN-α, IL-12, IL-6, IL-17, IL-10, IL-5, IL-2R, ST2/IL-1R4, CCL2, CCL3, CXCL9, M-CSF and E-Selectin, were significantly higher in presymptomatic/asymptomatic ZIKV infection (A-ZIKV group) when compared to the NI control group." (PMID 31748599, 2019).
dengue (11 papers, 2007 to 2023). "Comparing whole genome expression profiles between patients with acute versus convalescent dengue disease indicated significant abundance of transcripts of the chemokines CCL2 (4,287 fold), CCL8 (160 fold), CXCL10 (30 fold) and CCL3 (17 fold) during acute dengue." (PMID 21810247, 2011). "Recent clinical studies in endemic areas describe a correlation between dengue disease outcome and levels of CC chemokines, including CCL4/MIP1-β and CCL3/MIP1-α, both ligands for the CCR1 receptor, and for CCL2/MCP-1, the ligand for CCR2." (PMID 21206747, 2010). "Levels of the chemokine C-C ligands 2, 3 and 4 (CCL2, CCL3 and CCL4) have been correlated with severe dengue disease in humans in several studies, and mice lacking these chemokines have reduced lethality and milder disease during dengue infection." (PMID 28644404, 2017).
Granuloma (11 papers, 2010 to 2022). A compact, organized collection of mature mononuclear phagocytes, which may be but is not necessarily accompanied by accessory features such as necrosis. "In mice deficient in CCL3, a chemokine involved in eosinophil maturation, both hepatic and pulmonary granulomas are smaller, and eosinophils show decreased peroxidase activity." (PMID 36296298, 2022). "In accordance with its proposed role in promoting S. mansoni-induced granuloma formation, CCL3 expression peaked during granuloma development." (PMID 20161726, 2010).
ovarian carcinoma (11 papers, 2009 to 2025). A malignant neoplasm originating from the surface ovarian epithelium. "A decrease in CCL3 gene expression was also detected in macrophages after co-culture with ovarian cancer cells." (PMID 37445941, 2023). "Moreover, we further performed a cytokine array analysis, and HM‐macrophages coculture caused a significant increase in many inflammatory cytokines (G‐CSF, GM‐CSF, sICAM1, IL‐α, IL‐1β, IL‐1RA, IL‐6, CCL3, and TNFα), which are known to be abundantly present in ovarian cancer ascites." (PMID 35403834, 2022). "In a cultured cell line derived from the ascites of a patient with platinum resistant ovarian cancer (ET2), elevated levels of CCL2, CCL3, CCL4, CCL5, CXCL1, CXCL8 and CXCL10 were detected in the cultured media." (PMID 41424784, 2025). "A large number of cytokines have been reported as elevated in ovarian cancer ascites samples including IL-6, IL-8, IL-10, IL-15, IP-10/CXCL10, MCP-1/CCL2, Mip1α/CCL3, Mip1β/CCL4, MDC, and VEGF." (PMID 36860657, 2023). "In this study, we showed that EVs from ovarian cancer cells upregulated genes related to the inflammatory response, including immune cell–attracting cytokines (CCL2, CCL3/L1, CCL15, CCL18, and CCL20), interleukins (IL1B and IL32), and cell–cell adhesion transcripts (VCAM1 and ICAM1)." (PMID 40689422, 2025).
tuberculosis (11 papers, 2009 to 2025). A chronic, recurrent infection caused by the bacterium Mycobacterium tuberculosis. "Previous studies have found that S100A8 and MIP‐1alpha (CCL3) were remarkably elevated in PE of tuberculosis patients." (PMID 40170555, 2025). "In addition, the host exerts its anti-tuberculosis immune response and immune regulation function through immune molecules such as cytokines IFN-γ, IL-12, IL-1β, MIP-1α/CCL3, chemotactic factors, complement molecules, antimicrobial peptides, lysozyme, and βdefensins." (PMID 37631874, 2023). "Leucocyte activating chemokines such as CCL2, CCL3, and CXCL8 together with proinflammatory IFNγ, TNFα and downmodulatory IL10 play a central role in the restriction of M. tuberculosis infections, but is unclear whether these markers are indicative of tuberculosis disease severity." (PMID 20041183, 2009). "We did not observe any difference in M. tuberculosis induced CCL3 secretion, or CCL3 mRNA expression between patients with pulmonary or extrapulmonary TB with disease in single or multiple sites." (PMID 20041183, 2009).
anemia (10 papers, 2019 to 2025). A reduction in the number of red blood cells, the amount of hemoglobin, and/or the volume of packed red blood cells. "Elevated levels of CCL3 in the bone marrow is of particular interest as it has been proposed to suppress erythropoiesis and cause anaemia in MM patients." (PMID 37006302, 2023). "Preclinical studies and early clinical trials are investigating alternative strategies against MM-associated anemia by targeting the activin signaling pathway or the chemokine CCL3." (PMID 34638462, 2021). "Besides, MM cells can secret CCL3 to disrupt erythrocyte differentiation and cause anemia." (PMID 38475811, 2024). "Research shows that elevated CCL3 levels in the myeloma microenvironment impair erythrocyte differentiation of hematopoietic stem and progenitor cells (HSPCs), leading to anemia." (PMID 38475811, 2024). "The suppressive effect of CCL3 on erythropoiesis can be blocked by CCR1 antagonists, suggesting that CCL3/CCR1/phos-p38 is critical to CCL3-induced anemia in MM." (PMID 38475811, 2024). "Additionally, CCL3 enhances MM-mediated anemia by suppressing erythropoiesis through GATA1 downregulation." (PMID 38690165, 2024). "The inhibition of the CCL3/CCR1 pathway may therefore represent an additional promising strategy to overcome anemia in MM." (PMID 34638462, 2021).
colorectal cancer (10 papers, 2019 to 2025). A primary or metastatic malignant neoplasm that affects the colon or rectum. "These epidemiological findings contrast with data from patients with diagnosed colorectal cancer, where CCL3 levels are often elevated and associated with tumor progression and poor prognosis." (PMID 41153795, 2025). "They found that decreased blood levels of CCL3 may be linked to an increased risk of developing colorectal cancer in otherwise healthy individuals." (PMID 41153795, 2025). "Taken together, these six lines of evidence establish CCL3 as a central driver of colorectal cancer progression." (PMID 41153795, 2025). "After screening, CCL3, which is highly expressed in colorectal cancer tissues, was selected as the target factor." (PMID 35935327, 2022). "In this study, the cell, tissue, and animal experiments were conducted to prove that CCL3 is highly expressed in colorectal cancer." (PMID 35935327, 2022). "For developing new therapeutic targets and antitumor drugs, the effect of chemokine CCL3 and the related cytokine network on colorectal cancer should be investigated." (PMID 35935327, 2022). "CCL3 is highly expressed in a variety of cancers, but its expression in colorectal cancer has rarely been investigated." (PMID 35935327, 2022). "This study used cell, tissue, and animal experiments to prove that CCL3 is highly expressed in colorectal cancer and confirmed that CCL3 can promote the proliferation of cancer cells, and its expression is closely related to TRAF6/NF-κB molecular pathway." (PMID 35935327, 2022). "CCL3 might be particularly interesting in this regard, as it seems that CCL3 expression correlates with the proliferation, invasion, and migration of colorectal cancer cells, in addition to its feasible role in the development of CIPN." (PMID 41153795, 2025). "In addition, protein chip technology was used to examine colorectal cancer tissue samples and identify the key factors of chemokine CCL3 and the toll-like receptors/nuclear factor-κB (TLR/NF-κB) pathway in cancer and metastatic lymph nodes." (PMID 35935327, 2022). "Finally, the expression and significance of CCL3 in colorectal cancer tissues and its correlation with clinical pathology were studied by immunohistochemistry." (PMID 35935327, 2022). "In the present study, we confirmed that CCL3 is highly expressed in colorectal cancer tissues." (PMID 35935327, 2022). "However, rBFT1 promotes proliferation of colorectal cancer via CCL3-related pathway stimulation, providing an insight to the mechanisms of ETBF’s effect on CRC tumorigenesis and brings out a new perspective on prevention and therapy ways of CRC by employing an intestinal mucosal vaccine." (PMID 33981848, 2021). "CCL3 and CCR5 were expressed in paracancerous tissues, colorectal cancer tissues, and metastatic carcinoma, and the degree of expression was correlated with clinical stage and nerve invasion." (PMID 35935327, 2022). "The antibody array chemokine enrichment analysis chart shows that the chemokines CCL3, CCL4, and IL8 were highly expressed in colorectal cancer tissues and metastatic lymph nodes; however, they were downregulated in the normal, adjacent, and adenoma groups." (PMID 35935327, 2022). "The expression of chemokine CCL3 and receptor CCR5 is positively correlated with the expression of TRAF6 and NF-κB and can promote the proliferation, invasion, and migration of colorectal cancer through TRAF6 and NF-κB pathway." (PMID 35935327, 2022). "The expression of chemokine CCL3 and receptor CCR5 was positively correlated with the expression of TRAF6 and NF-κB and could promote the proliferation, invasion, and migration of colorectal cancer cells through TRAF6 and NF-κB." (PMID 35935327, 2022). "Also, the results confirmed that CCL3 and C-C motif chemokine receptor 5 (CCR5) were expressed in adjacent tissues, colorectal cancer tissues, and metastatic cancer." (PMID 35935327, 2022).
colorectal cancer (continued). "However, the current literature on CCL3L1 in the context of colorectal cancer or chemotherapy-induced peripheral neuropathy is very limited, and no studies have directly compared its role to that of CCL3 in these settings." (PMID 41153795, 2025). "However, it does not address variations in CCL3 expression across different stages of established colorectal cancer." (PMID 41153795, 2025).